BCL6 (BCL6 transcription repressor)
Diseases named in the same sentence as BCL6 in open-access papers (continued):
Sharing a sentence is not in itself a finding about the gene and the disease.
diffuse large B-cell lymphoma (continued). "Quantitative multiplexed microscopy reveals that a subpopulation of cells that coexpress MYC and BCL2 without BCL6 govern clinical outcomes in diffuse large B-cell lymphoma, underscoring the importance of analyzing protein coexpression patterns at single-cell resolution." (PMID 37071673, 2023). "Postoperative pathology revealed diffuse large B-cell lymphoma (DLBCL), with immunohistochemically related positive indicators, including CD20, CD79a, LCA, MUM-1, PAX5, C-MYC, BCL-2, and BCL-6, in all patients." (PMID 35734472, 2022). "Histological examination of the specimen provided a diagnosis of diffuse large B-cell lymphoma (DLBCL) with immunohistochemistry staining showing positive results for CD20, CD79, Bcl-2 and Bcl-6." (PMID 31752767, 2019). "The isolated MYC+/BCL6+/BCL2− subset, more frequent in germinal center B-cell like diffuse large B-cell lymphoma, had significantly better survival compared with the isolated MYC+/BCL2+/BCL6− subset (more frequent in activated B-cell like diffuse large B-cell lymphoma)." (PMID 26573234, 2016). "The diffuse large B-cell lymphomas (DLBCL) and reactive lymph node hyperplasia (RLH) tissues were embedded in paraffin and then stained with H&E or immunohistochemical staining of Bcl6 for histology examination." (PMID 27815824, 2016). "Neither BCL6 translocation alone (more frequent in activated B-cell like diffuse large B-cell lymphoma) nor in combination with MYC translocation (observed in 2.0% of diffuse large B-cell lymphoma) predicted poorer survival in diffuse large B-cell lymphoma patients." (PMID 26573234, 2016). "Though it has been discovered that BCL2 and BCL6 proteins have an impact on diffuse large B-cell lymphoma development and outcome, they may not be good prognostic markers." (PMID 23289441, 2013). "However, when we analyzed 5 cases of diffuse large B-cell lymphoma (DLBCL) with histologically documented BCL-6 expression, nuclear aggregates were not detectable." (PMID 24146931, 2013). "PTLD expressing the BCL6+/MUM1+/-/CD138− profile reflect B-cells actively experiencing the GC reaction, and comprise diffuse large B-cell lymphoma (DLBCL) centroblastic and Burkitt lymphoma." (PMID 21416004, 2009). "In comparison, previously discovered CRBN-based heterobifunctional BCL6 degraders did not achieve complete BCL6 degradation and failed to induce a significant phenotypic response in diffuse large B-cell lymphoma (DLBCL)." (PMID 38607017, 2024). "MYC translocation occurs in 8–14% of diffuse large B-cell lymphoma (DLBCL), and may concur with BCL2 and/or BCL6 translocation, known as double-hit (DH) or triple-hit (TH)." (PMID 38184753, 2024). "The third pathological investigation revealed non-germinal center B cell like (GCB) diffuse large B cell lymphoma (DLBCL) with invasion of striated muscle tissue, positive for Bcl-2 (90%+), Bcl-6 (60%+), CD20 (3+), Ki67 (80%+), MUM1 (80%+) and c-myc (50%+)." (PMID 40406106, 2025). "Expressions of Bcl-6, CD10, and IRF4 are used in immunohistochemical stains to separate diffuse large B cell lymphomas into GC and non-GC subtypes." (PMID 26829983, 2016). "The immunophenotype (CD10−/BCL6+/MUM1+) supported a nongerminal center B-cell origin, raising concern for a diffuse large B-cell lymphoma (DLBCL)." (PMID 27213065, 2016). "Since these markers are also found in diffuse large B-cell lymphoma (DLBCL), the absence of CD10 and BCL6 can effectively rule out BL." (PMID 40428800, 2025). "A CT-guided adrenal biopsy showed diffuse large B-cell lymphoma (DLBCL) with expression of CD20, CD10, BCL-6, and MUM-1, but without CD5 expression." (PMID 40969788, 2025).
diffuse large B-cell lymphoma (continued). "Diffuse large B-cell lymphoma (DLBCL) was indicated by the tumor cells' positive results for CD20 and BCL6, as well as negative results for CK and CD3." (PMID 39610570, 2024). "The patient was an 86-year-old Caucasian woman originally diagnosed in September 2014 with Stage IVA diffuse large B-cell lymphoma (DLBCL) of non-GCB origin using the Hans algorithm (CD10 negative; BCL6, MUM1 positive)." (PMID 35323358, 2022). "Recent studies showed that diffuse large B-cell lymphoma (DLBCL) could be classified into germinal centre B cell-like (GCB) and non-germinal centre B cell-like (non-GCB) phenotypes according to CD10,Bcl-6 and MUM1 expression." (PMID 22726454, 2012).
breast cancer (75 papers, 2007 to 2026). A primary or metastatic malignant neoplasm involving the breast. "BCL6 expression also promotes tumor angiogenesis and is associated with human breast cancer progression and poor prognosis." (PMID 38951817, 2024). "BCL6 was the second most significant in the results and it is associated with survival of breast cancer cells." (PMID 36077026, 2022). "Another variant was found in BCL6 that is reported to contribute to the development of breast cancer." (PMID 35625741, 2022). "Recent studies have implicated genomic amplification of the BCL6 locus in certain solid tumors such as glioma, breast cancer, and ovarian cancer." (PMID 36377663, 2022). "BCL6 has also been implicated in an expanding spectrum of solid and hematologic tumors, including leukemia, breast cancer, and NSCLC." (PMID 35163005, 2022). "Recent studies have also implicated BCL6 overexpression in certain solid tumors such as glioblastoma, breast cancer, and ovarian cancer." (PMID 36377663, 2022). "Herein, we demonstrate a new role played by screen hit BCL6 in paclitaxel resistance in breast cancer and reveal associations with expression of some of the screen hits and breast cancer patient response to chemotherapy treatment that includes paclitaxel." (PMID 33932086, 2021). "Our data are aligned with a recent report showing that Bcl6 is upregulated in breast cancer and is associated with poor prognosis, including advanced stages and triple negative molecular subtypes." (PMID 29854311, 2018). "Conversely, further studies revealed that Bcl-6 expression was associated with disease progression and poor survival of breast cancer patients." (PMID 27237631, 2016). "Amongst the proteins linked to miR-127 activity and breast cancer development, are BCL6 and Tudor-SN." (PMID 26097876, 2015). "The basis of the link between miRNA activity and CD-induced breast cancer seems to be an interconnected web of increased NF-κB activity and BCL6 expression, likely linked to and promoted by the CD-induced decrease in miR-127 and miR-146b." (PMID 26097876, 2015). "Expression of BCL6 protein was associated with tumor size, lymph node metastasis, advanced clinical stages, higher tumor grade and also Ki67 labeling index in breast cancer." (PMID 24917186, 2014). "Another most recent study showed that high expression of BCL6 protein associated with unfavorable clinical outcome of ER-positive and premenopausal breast cancer patients." (PMID 24917186, 2014). "BCL6 protein was highly expressed in breast cancer cell lines and tissue specimens and expression of BCL6 protein was associated with disease progression and poor survival of breast cancer patients." (PMID 24917186, 2014). "Manipulation of BCL6 expression using the gain and loss of function approaches affected breast cancer cell viability, apoptosis, migration, invasion and gene expression in vitro and in nude mice." (PMID 24917186, 2014). "Future studies will further investigate the underlying molecular mechanisms by which BCL6 is overexpressed in breast cancer and BCL6 expression contributes to breast cancer progression." (PMID 24917186, 2014). "We further showed that miR-127 is down-regulated in breast cancer tissuesand that this down-regulation is associated with up-regulation of BCL6." (PMID 24282530, 2013). "Bcl-6, a homolog of the up-regulated Bazf gene, has been found to be up-regulated in breast cancer and associated with higher HIF-1α levels." (PMID 20657781, 2010). "We chose BCL-6 for further analysis because it was predicted by all three algorithms and was also previously implicated in promoting breast cancer progression." (PMID 20932331, 2010). "While previous studies have predominantly identified BCL6 as a hematopoietic tumor-specific oncogene, intriguing emerging data have also linked BCL6 to the regulation of the progression of solid tumors, such as lung cancer, breast cancer, and ovarian cancer." (PMID 40777995, 2025).
breast cancer (continued). "Furthermore, nuclear localization of STAT5A was negatively correlated with BCL6 expression in breast cancer tissue samples, where BCL6 expression is associated with increased proliferation and cell cycle progression and reduced differentiation." (PMID 40507264, 2025). "Thus, BCL6 has been found to be highly expressed in breast cancer and associated with enhanced disease progression and decreased patient survival, with its overexpression increasing tumor growth and invasion in a xenograft model." (PMID 39456751, 2024). "Recent study also found that BCL6 has been implicated in the development of type B acute lymphocyte leukaemia, chronic myeloid leukaemia, breast cancer and non-small-cell lung carcinoma, suggesting that it might be a potential drug target." (PMID 36945884, 2023). "Furthermore, BCL6 expression is correlated with disease progression and poor overall survival, and targeting BCL6 results in reduced growth and loss of breast cancer cell viability." (PMID 26697522, 2015). "We also explored the underlying molecular events of BCL6 action in breast cancer cells." (PMID 24917186, 2014). "Thus, in this study, we first determined expression of BCL6 protein in breast cancer tissues and cell lines, and then associated BCL6 expression with disease progression and prognosis." (PMID 24917186, 2014). "However, contradicted data did show that BCL6 expression was inversely associated with breast cancer cell lymph node metastasis, but associated with survival of breast cancer patients." (PMID 24917186, 2014). "Of these genes, BCL-6 is regarded as a proto-oncogene that was originally characterized as a regulator of B-lymphocyte development and growth and has been implicated in many human malignancies, including breast cancer." (PMID 25477702, 2014). "Our current study demonstrated that high expression of BCL6 associated with tumor size, lymph node metastasis, advanced clinical stages, higher tumor grade, and Ki67 labeling index as well as poor prognosis of breast cancer." (PMID 24917186, 2014). "Our further study showed that miR-339-5p could significantly decrease tumor cell migration and invasion capacity, which associated with downregulation of BCL-6 expression in breast cancer cells." (PMID 20932331, 2010). "Our current study revealed that miR-339-5p could inhibit expression of BCL-6 mRNA, which is associated with suppression of the migration and invasion of breast cancer cells." (PMID 20932331, 2010). "BCL6 is an important transcriptional regulator in BC and has been reported to be highly expressed in breast cancers." (PMID 40700427, 2025). "TNBC cells, however, are reported to be more sensitive to inhibition of BCL6 compared to other breast cancer subtypes." (PMID 40700427, 2025). "Prolactin-induced STAT5 can also repress expression of B-cell lymphoma 6 (BCL6) in breast cancer cells through direct binding to the gene." (PMID 40507264, 2025). "In the mFMC group, there was marked protein expression of BCL6, TXNRD3, CP and BIRC6, which have been linked with poor prognosis in human breast cancer." (PMID 38951817, 2024). "Hsa-miR-127-5p targets BCL6 and disrupts NF-κB signaling in breast cancer and hepatocellular carcinoma, inhibiting cancer development." (PMID 39684278, 2024). "Emerging literature supports that restoration of ZBTB16 led to induction of G2/M phase arrest and reversal of EMT through antagonizing BCL6/ZBTB27 breast cancer." (PMID 38789960, 2024). "BCL6, a class of transcriptional repressors, was previously reported to promote the growth, migration, and metastatic ability of breast cancer cells." (PMID 35484551, 2022). "According to data derived from The Cancer Genome Atlas (TCGA), the BCL6 locus is also predominantly amplified in primary breast cancer and is correlated with a worse prognosis." (PMID 35503721, 2022). "BCL6 is related to the stress response in breast cancer, lung cancer, glioma, and other solid tumors." (PMID 36531232, 2022).
breast cancer (continued). "Studies have found that micro RNA339‐5p (miR‐339‐5p) target the gene B‐cell lymphoma 6 (BCL6) and the expression of BCL6 protein was related to the breast cancer progression." (PMID 34651424, 2021). "Mir-339-5p acts as a tumor suppressor gene and its expression is required to inhibit cell migration and invasion in breast cancer cells in a mechanism that involves at least the B-cell lymphoma 6 (BCL6) protein." (PMID 34513655, 2021). "To expand these studies to additional cell lines, we assessed expression of BCL6 in a panel of breast cancer cell lines to identify a cell line which had high levels of BCL6." (PMID 33932086, 2021). "In summary, the genome‐wide shRNA knockdown screen has identified BCL6 as a potential targetable resistance biomarker of paclitaxel response in breast cancer." (PMID 33932086, 2021). "A study indicated that B-cell CLL/lymphoma 6 (BCL6) promotes EMT via enhancing the ZEB1-mediated transcriptional repression of E-cadherin in breast cancer cells." (PMID 34217266, 2021). "Our data suggest that decreased BCL6 increases paclitaxel response in breast cancer by shifting the cell cycle arrest induced by paclitaxel toward a more prolonged G1/S arrest." (PMID 33932086, 2021). "An in vivo genome‐wide shRNA screen identified several potential biomarkers of paclitaxel response in breast cancer, including transcriptional repressor BCL6 as a biomarker of paclitaxel resistance." (PMID 33932086, 2021). "The study showed that PRL inhibited the expression of BCL6 and upregulated the expression of miR‐339‐5p in breast cancer cells." (PMID 34651424, 2021). "Here, we explored the associations among ZBTB16, BCL6, and ZBTB28 and their relevance in breast cancer." (PMID 32517789, 2020). "Expression of ZBTB16 and ZBTB28 in most breast cancer cell lines was low or silenced but BCL6 was high." (PMID 32517789, 2020). "The collective results demonstrated that ZBTB16 exerts significant tumor suppressor effects through upregulation of ZBTB28 and downregulation of BCL6 and supported its identity as a prognostic biomarker to improve treatment outcomes of breast cancer." (PMID 32517789, 2020). "BCL6 induces EMT by promoting the ZEB1-mediated transcription repression of E-cad in breast cancer cells." (PMID 31988090, 2020). "Over-expression of miR-127 inhibits breast cancer cell proliferation, enhances apoptosis, and reduces migration and invasion via targeting BCL6." (PMID 32979257, 2020). "In G3 breast cancer, rearrangement of BCL6 showed a frequency of 4.9% ± SE 0.45%, vs a significant decrease to 1.62% ± SE 0.15% and 1.40% ± SE 0.29% in G1/G2 breast cancer and in control respectively." (PMID 29854311, 2018). "The transcriptional repressor, BCL6, appears to be important to promote mesenchymal properties of breast cancer cells." (PMID 30558204, 2018). "Real time-PCR, Bcl6 mRNA showed significant increase expression in G3 breast cancer (0.5 ± SE 0.05) compared with G1/G2 (1.5 ± SE 0.30) and control (1 ± SE 0.1) specimens." (PMID 29854311, 2018). "Morphometric analysis showed a significant difference (4.0% ± SE 0,3%) in Bcl6 expression in G3 breast cancer compared with G1/G2 breast cancer (1,1% ± SE 0,3%) and controls (0,50% ± SE 0,1%)." (PMID 29854311, 2018). "The high expression of BCL6 in breast cancer cells promoted cell proliferation, migration, and invasion and indicated survival poor prognosis in both vitro and xenografts models." (PMID 30420967, 2018). "E-cadherin is often downregulated during cell invasion to allow detachment from the tumor, and BCL6 serves a transcriptional repressor of E-cadherin in breast cancer cells." (PMID 30558204, 2018).